CCL4 (C-C motif chemokine ligand 4)
Diseases named in the same sentence as CCL4 in open-access papers (continued):
Sharing a sentence is not in itself a finding about the gene and the disease.
liver fibrosis (continued). "In the current study, we found that SIRT2 expression were reduced in the liver of CCL4-induced hepatic fibrosis, and specific deletion of Sirt2 in hepatocyte aggravated CCl4-induced hepatic fibrosis and upregulated TGF-β regulated genes expression." (PMID 37777567, 2023). "On the one hand, a protective role was shown demonstrating decreased accumulation of ECM and a lower number of αSMA+ cells upon overexpression of MMP13 in the chronic CCL4-induced model of liver fibrosis." (PMID 37207229, 2023). "Specifically, FVBN mice gain less weight in response to over-nutrition compared with C57BL6 mice and are protected against CCL4-induced hepatic fibrosis, while both strains develop hepatic steatosis and insulin resistance with high-fat or WD feeding." (PMID 37165006, 2023). "In this study, CCL4 was used to build a mouse liver fibrosis model, and the treatment groups were treated with 100 and 200 mg/kg of anthocyanins daily by gavage." (PMID 37324880, 2023). "MiR-132, which is highly expressed in cirrhotic patients, is also an important promoter of hepatic fibrosis, as evidenced by an anti-miR-132 approach in a mouse model of fibrosis (CCL4-treated mice)." (PMID 38067261, 2023). "It was also found that rapamycin significantly reduced the level of Th17 cells and the expression level of ROR-γT in the CCL4-induced liver fibrosis model." (PMID 36759593, 2023). "In vivo injection of hBMSC-Exos has been shown to effectively alleviate CCL4-induced liver fibrosis in rats and restore liver function." (PMID 35787632, 2022). "B cells depletion in mice results in a reduction of CCL4-induced liver fibrosis and improves fat-induced inflammation." (PMID 36386790, 2022). "ALT and AST are the indicator of liver function, and its serum level is significantly increased when liver damage is even more severe; these results indicated that HBO1 showed the therapeutic effect on CCL4-induced liver fibrosis." (PMID 36524217, 2022). "Currently, we are still working on optimizing the treatment of RSV in CCL4-induced liver fibrosis, and we believe the work will be benefit to disclose the protective window of time of RSV and clarify the molecular and cellular mechanisms in future." (PMID 35080697, 2022). "CCL4-induced liver fibrosis can be alleviated by vildagliptin by targeting ERK1/2, p38α and NF-κB signals." (PMID 36267567, 2022). "CCR2 (a receptor for CCL2) and CCR5 (a receptor for CCL3 and CCL4) have been proposed to be targets for antifibrotic therapy due to their ability to promote liver fibrosis and macrophage infiltration." (PMID 35662287, 2022). "The protective effect of FOXA2 against CCL4-induced hepatic fibrosis in mice, was attributed to FOXA2 downregulation in hepatocytes." (PMID 35907883, 2022). "In CCL4-induced liver fibrosis model mice, IPA aggravated CCL4-induced liver fibrosis injury through transforming growth factor-β1 (TGF-β1) and the Smad signaling pathway." (PMID 35370963, 2022). "Similar hyporesponsive effects of α-GalCer on liver fibrosis were also found in chronic CCL4-induced liver injury." (PMID 35950602, 2022). "The in vivo inhibition of miR-142-5p with locked nucleic acid-modified oligonucleotides reduces CCL4-induced liver fibrosis and bleomycin-induced lung fibrosis in mice." (PMID 35230645, 2022). "The results of immunohistochemical staining showed that the mice in the experimental group injected with CCL4 exhibited obvious liver fibrosis." (PMID 36524217, 2022). "Rev-Erb agonist (SR9009) protected against CCL4-induced liver fibrosis in mice by upregulation of the expression of the clock genes Bmal1, Clock, Per2, Cry1, and RORα." (PMID 36361737, 2022). "In 2017, IVA337, another new PPAR (including PPARA) agonist, revealed its ability to suppress the proliferation and activation of human hepatic stellate cells (HSCs), and alleviate mouse liver fibrosis induced by CCL4." (PMID 35264957, 2022).
liver fibrosis (continued). "Se supplementation reduced the number of CCL4-induced hepatic stellate cells (HSCs) in mice, a key factor in the pathogenesis of liver fibrosis." (PMID 35204232, 2022). "The anti-fibrotic effect of miRNAs in MSC-EVs has become a focus of research into CCL4-induced liver fibrosis in rats." (PMID 35787632, 2022). "Administration of PAs into CCl4-induced rats’ liver fibrosis led to a significant (P < 0.05) amelioration at the levels of these apoptotic regulating proteins compared with CCL4-treated rats." (PMID 35881285, 2022). "To investigate the effect of SSd on liver injury, we established a mouse model of CCL4-induced liver injury and liver fibrosis." (PMID 35694250, 2022). "Herein, for the first time, LUT-Ex was prepared and its efficacy in the treatment of CCL4-induced liver fibrosis was assessed versus either LUT-suspension or blank exosomes." (PMID 36330597, 2022). "It has been shown in a murine model of liver fibrosis with CCL4 that hepatic Tdo2 is upregulated in Ido1−/− mice." (PMID 35563591, 2022). "Because arginine can inhibit CCL4-induced liver fibrosis in mice, inhibition of arginine synthesis would ultimately lead to hepatic fibrosis." (PMID 36278176, 2022). "In the current study, to evaluate the therapeutic effect of HBO1 as a molecular target on liver aging and fibrosis, naturally-aged mice and CCL4-induced liver fibrosis mice were used as animal models, and multiple experiments were performed." (PMID 36524217, 2022). "The rat in the CCL4-induced group displayed elevated liver fibrosis level, as evidenced by accumulated collagen in livers by Masson and Sirus Red stainings." (PMID 35585044, 2022). "One is a model of natural aging-related liver fibrosis, and another is a model of CCL4-induced liver fibrosis." (PMID 36524217, 2022). "In vitro and in vivo studies demonstrated that Rev-Erbα agonist reduced fibrosis in rat HSCs and CCL4-induced liver fibrosis." (PMID 36361737, 2022). "For example, paeoniflorin inhibits HIF-1α translation by mTOR and attenuates CCL4-induced liver fibrosis in rats." (PMID 35682354, 2022). "In CCL4-induced liver fibrosis, artemether significantly downregulated many markers of HSC activation, including α-SMA, Col1a1, and fibronectin, and inhibited profibrotic receptors such as TGF-βR1, PDGF-βR and epidermal growth factor receptor." (PMID 36353498, 2022). "The widely used animal models of liver fibrosis were mainly two types including hepatotoxic substance induction and surgical ligation, such as CCL4, TAA, DDC, and CBDL." (PMID 34545977, 2022). "For example, although IPA effectively inhibits the activation of hepatic stellate cells and prevents liver fibrosis, it aggravates CCL4-induced liver fibrosis through the Smads signaling pathway in the presence of CCL4." (PMID 36615808, 2022). "Studies have found that the autophagy of BDL and CCL4-induced liver fibrosis can be activated to promote liver injury by activating the TGF-β1/Smads signaling pathway and inhibiting PI3K/Akt signaling pathway and regulating cross-talk between the two pathways." (PMID 35529927, 2022). "To verify the role of paracrine factors, particularly EXOs during MSCs treatment, we transplanted MSCs or GW4869 pre-treated MSCs into CCL4-induced mouse model of liver fibrosis." (PMID 35858897, 2022). "In other studies, Se and vitamin E combined administration also reduced liver fibrosis and promoted apoptosis of activated HSCs in CCL4-induced rat hepatic injury." (PMID 35204232, 2022).
liver fibrosis (continued). "The present study is aimed at elucidating the impact of heparanase on the pathogenesis of liver fibrosis, using the well-established CCL4-induced mouse model." (PMID 35805119, 2022). "CXCL12-CXCR4 axis activation induced HSC proliferation and increased the production of collagen I in a CCL4-induced hepatic fibrosis mouse model." (PMID 36010588, 2022). "In mice liver fibrosis model induced by CCl‐4, collagen fibre decreased obviously in DHFR knock‐down mice." (PMID 34626074, 2021). "To evaluate the effects of MitoQ on hepatic fibrosis, we established a model of CCL4-induced hepatic fibrosis." (PMID 34825063, 2021). "For example, downregulation of the LOXL1 enzyme led to reduction of collagen and elastin expression alongside decreased elastin cross-linking in the murine CCL4 model of liver fibrosis." (PMID 33498156, 2021). "Other types of nanoparticles have also been discovered to target HSC by surface engineering with vitamin A. Administration of vitamin A grafted nanoparticles in CCL4-induced liver fibrosis showed significant reduction in collagen production in mice." (PMID 34064375, 2021). "In this study, we reported that the transplantation of HepLPCs, with high levels of CD24 expression, effectively attenuated CCL4-induced liver fibrosis." (PMID 33859762, 2021). "As shown in the heatmap, inflammatory mediators were expressed significantly, with higher levels in the CCL4-induced liver fibrosis mice than in healthy controls (P value TLR-2 0.02, TLR-4 0.003, and TNF-α 0.03)." (PMID 34549998, 2021). "Chlorogenic acids protect against CCL4-induced liver fibrosis through the suppression of oxidative stress in the liver and HSCs." (PMID 34239589, 2021). "Using BM-MSCs with induced colony-stimulating factor-1 in a mouse CCL4 (C-C Motif Chemokine Ligand 4) model of cirrhosis synergistically improved reduced liver fibrosis and improved hepatocyte proliferation." (PMID 35096805, 2021). "In mice with CCL4-induced liver fibrosis, up-regulated CXCL1 expression in hepatic stellate cells has been reported to promote it activation and modulate liver fibrogenesis." (PMID 34395462, 2021). "Over-expression Erk1 significantly enhanced the activity of HIF1α under hypoxia, HIF1α and Erk expression increased with CCL4-induced rat liver fibrosis." (PMID 34853322, 2021). "DHFR silence led to decrease in cell viability of activated Lx‐2 cells and M1 macrophage polarization, as well as liver fibrosis remission in CCL‐4‐induced liver fibrosis mice." (PMID 34626074, 2021). "A recent study found that in CCL4-induced liver fibrosis mice, oral IPA intervention (20 mg/kg/d) aggravated liver damage and fibrosis by activating HSCs via the TGF-β1/Smad signaling pathway." (PMID 34966278, 2021). "Caffeic and ferulic acids have been shown to prevent liver damage and ameliorate liver fibrosis in CCL4-treated rats." (PMID 34239589, 2021). "Data from the present study showed for the first time that SNS effectively reverses CCL4-induced liver fibrosis in vivo and facilitates recovery of liver function." (PMID 34276360, 2021). "The study concludes that margatoxin alleviates CCL4 induced hepatic fibrosis in mice, possibly through macrophage polarization, cytokine secretion and STAT signaling." (PMID 34064375, 2021). "We next investigated the anti-inflammatory effects of 3D-Exo in the mouse liver fibrosis model which was induced by CCL4 in conjuction with employing alcohol for 8 weeks." (PMID 34930304, 2021). "The in vivo administration of HACY not only induced the conversion of mature hepatocytes (MHs) to CD24+ progenitor cells but prevented the activation of HSCs, thus leading to enhanced improvement of liver fibrosis in CCL4-treated mice." (PMID 33859762, 2021). "Subsequently, we constructed a CCL4-induced liver fibrosis model in mice and checked the liver injury levels at 4 and 8 weeks after induction." (PMID 34853322, 2021).
liver fibrosis (continued). "miR-214 also plays an important role in liver fibrosis by regulating the expression of suppressor of fused homolog protein, and knocking down its expression alleviates liver fibrosis in carbon tetrachloride (CCL4)-treated mice." (PMID 34360904, 2021). "Contrary to previous impressions, high-frequency administration of GS9973 will aggravate CCL4-induced liver fibrosis, which is especially unsuitable for patients with cholestasis whose clinical features are bile duct obstruction." (PMID 34853322, 2021). "Recently, it has been revealed that margatoxin protects mice from CCL4-induced liver fibrosis by decreasing the expression of M1 macrophage phenotype and increasing M2 macrophage." (PMID 34064375, 2021). "MALAT1 and METTL3 expressions presented a time-dependent increase with the progression of CCL4-induced liver fibrosis." (PMID 34839365, 2021). "When these EVs were administered to mice with CCL4-induced liver injury, hepatocellular damage and liver fibrosis were suppressed in the healthy mouse-derived EV group, and inflammatory cytokines and transaminases in the blood were reduced." (PMID 34360904, 2021). "Previous studies reported that PRI-724 attenuated HSC activation and ECM accumulation in CCL4-induced mouse model of liver fibrosis and decreased fibrosis severity in liver fibrosis mouse model induced by hepatitis C virus (HCV)." (PMID 34326871, 2021). "Inhibition of TIM-4 with mAB or TIM-4 siRNA decreases liver fibrosis by lessening hydroxyproline and collagen deposition in CCL4-induced liver fibrosis." (PMID 34064375, 2021). "CXCR4 antagonist AMD 3100 octahydrochloride hydrate grafted nanoparticles have been shown to inhibit the progression of CCL-4 induced liver fibrosis in mice." (PMID 34064375, 2021). "In rat models of CCL4-induced hepatic fibrosis and fructose fed-NAFLD, the hepatic RAS was over-activated and imbalanced, and the ratios of ACE/ACE2, AngII/Ang1-7, and AT1R/Mas were upregulated." (PMID 32322207, 2020). "In one study, the benefit of concurrent treatment with an allosteric anti-LOXL2 mAb (AB0023) in a reversible model of CCL4-induced liver fibrosis was assessed." (PMID 32296422, 2020). "In sharp contrast, in the GS341-Fab-treated livers, collagenase activity co-localized with the collagen fibers, resembling the collagenolytic activity displayed at the resolution phase of CCL4-induced liver fibrosis (120 h)." (PMID 32296422, 2020). "In the present study, we found that CCL4‐induced liver fibrosis mice showed KCs were predominant number of macrophages in liver (>90%) with high levels of TIM‐4 expression instead of other liver non‐parenchymal cells." (PMID 31755616, 2020). "On the other hand, conditional liver-specific ASK1 overexpression protected mice against HFD- and CCL4-induced liver fibrosis." (PMID 32724454, 2020). "We successfully established CCL‐4‐induced liver fibrosis models and found that there was extensive destruction of liver structure, along with abnormal collagen deposition, but olive‐induced models have normal liver architecture compared with the NC group." (PMID 31755616, 2020). "Preclinical models used for validation of elafibranor include db/db mice, CCL4-induced liver fibrosis model and hApoE2-KI mice coupled to WD." (PMID 33343375, 2020). "In conclusion, nintedanib demonstrated antifibrotic and anti-inflammatory activity, showing therapeutic potential in this experimental mouse model of CCL4-induced hepatic fibrosis." (PMID 32337244, 2020). "Similar to our findings, another preclinical model of CCL4-induced liver fibrosis found that nintedanib significantly attenuated collagen accumulation and hepatic stellate cell activation, inhibiting intrahepatic inflammation and angiogenesis." (PMID 32337244, 2020). "Our study showed that the CCL4-induced liver fibrosis model resulted in more than 10-fold increase in the serum levels of PDGF-AB and that nAG treatment significantly reduced these elevated levels." (PMID 31275996, 2019).
liver fibrosis (continued). "Our data indicate that KFXOL dramatically inhibited TIMP-1 expression, which is consistent with previous observations on the activity of P. americana extracts in rats with CCL4-induced hepatic fibrosis." (PMID 31885648, 2019). "The degree of liver fibrosis was also significantly reduced in the CCL4/nAG group compared to the CCL4 group." (PMID 31275996, 2019). "In contrast, TLR7 has been identified as a protective factor in hepatic fibrosis development in both CCL4 and BDL murine fibrosis models." (PMID 31717860, 2019). "Hong-wei Zhao showed that OM played a significant antifibrotic role via modulation of TLR4-dependent inflammatory and TGFβ1-signaling pathways in CCL4 induced hepatic fibrosis rats." (PMID 31221141, 2019). "Similar to our findings, a beneficial role of the commensal microbiota, in preventing murine CCL4-induced liver fibrosis has been shown." (PMID 30646522, 2019). "Chronic intraperitoneal administration of CCL4 is a frequently used model to induce liver fibrosis in mice and rats." (PMID 30375438, 2018). "It has been reported that MAPK and NF-κB pathways had a synergistic effect on CCL4-induced liver fibrosis." (PMID 30662889, 2018). "Reminiscent to our study, iNKT cells require NKG2D surface expression to inhibit liver fibrosis after IL-30 treatment by selectively removing CCL4-activated hepatic stellae cells through an NKG2D/RAE-1interaction." (PMID 29868013, 2018). "More importantly, Lgr5+ liver stem cell transplantation relieved CCL4-induced liver fibrosis, and when Lgr5 was knocked down, the mice developed more severe fibrosis." (PMID 29079780, 2017). "In two different experiments, male Vistar, and Sprague Dawley Rat models ranging from 200±60, corresponding to an age of approximately 10 weeks were utilized in order to induce CCL4 treated liver fibrosis." (PMID 29511482, 2017). "In this study, we aim to establish and present an efficient protocol to induce liver fibrosis by CCL4 as a toxin reagent in rat models." (PMID 29511482, 2017). "This study is presenting an effective method of inducing liver fibrosis by CCL4 as a toxin in two different breeds of rat models." (PMID 29511482, 2017). "A recent study demonstrated the involvement of TLR5-mediated MAPK signaling in CCL4-induced liver fibrosis development, as manifested by enhanced collagen accumulation and inflammatory infiltration in HSCs." (PMID 28472150, 2017). "In a murine model of acute and chronic CCL4-induced liver fibrosis, we observed a rapid, marked and persistent reduction in ERG expression." (PMID 29026072, 2017). "Another microarray performed in in vivo CCL4-induced hepatic fibrosis mouse model demonstrated significant down-regulation of miR-29 family, and they validated their result on human samples." (PMID 26999230, 2016). "In vivo, Masson staining and quantification of collagen evaluation showed hPP10-GCLC treatment significantly decreased collagens content in rat model, including CCL4-induced liver fibrosis and pig serum-induced liver fibrosis model." (PMID 27081693, 2016). "Upon challenge with CCL4, Ccr2−/− mice showed markedly reduced liver fibrosis compared with the wild-type mice." (PMID 26436920, 2015). "More importantly, transferring M(IL-13) that were transduced with either miR-130a-3p mimics or miR-142-5p ASO into the CCL4-treated Ccr2−/− mice rendered much milder liver fibrosis compared with transferring the untransduced M(IL-13) cells." (PMID 26436920, 2015). "More importantly, inhibiting miR-142-5p and increasing miR-130a-3p expression with LNA-modified oligonucleotides alleviated both CCL4-induced liver fibrosis and bleomycin-induced lung fibrosis, highlighting the therapeutic importance of these miRNAs." (PMID 26436920, 2015). "We found that the severity of hepatic fibrosis was increased by enhancing particles on the liver surface, and there was liver volume with the prolonged treatment of CCL4." (PMID 26517671, 2015).